EPHB1 (EPH receptor B1)
Description:
Receptor tyrosine kinase which binds promiscuously transmembrane ephrin-B family ligands residing on adjacent cells, leading to contact-dependent bidirectional signaling into neighboring cells. The signaling pathway downstream of the receptor is referred to as forward signaling while the signaling pathway downstream of the ephrin ligand is referred to as reverse signaling. Cognate/functional ephrin ligands for this receptor include EFNB1, EFNB2 and EFNB3. During nervous system development, regulates retinal axon guidance redirecting ipsilaterally ventrotemporal retinal ganglion cells axons at the optic chiasm midline. This probably requires repulsive interaction with EFNB2. In the adult nervous system together with EFNB3, regulates chemotaxis, proliferation and polarity of the hippocampus neural progenitors. In addition to its role in axon guidance also plays an important redundant role with other ephrin-B receptors in development and maturation of dendritic spines and synapse formation. May also regulate angiogenesis. More generally, may play a role in targeted cell migration and adhesion. Upon activation by EFNB1 and probably other ephrin-B ligands activates the MAPK/ERK and the JNK signaling cascades to regulate cell migration and adhesion respectively. Involved in the maintenance of the pool of satellite cells (muscle stem cells) by promoting their self-renewal and reducing their activation and differentiation (By similarity).
Synonyms: hEK6; NET; ELK; EPHT2
Tractability: Small molecule: an approved drug acts on it; a structure with a bound ligand is known; a high-quality ligand is known; it belongs to a druggable protein family. Antibody: UniProt places it where antibodies can reach, with high confidence; its Gene Ontology location is reachable by antibodies, with high confidence; UniProt predicts a signal peptide or a membrane-spanning region; the Human Protein Atlas places it where antibodies can reach. PROTAC: UniProt records ubiquitination sites on it; ubiquitination databases record sites on it; its protein half-life has been measured; a small molecule that binds it is known.
Target class: Tyrosine protein kinase Eph family; Protein Kinase; TK protein kinase group; Kinase; Enzyme
Gene: Protein-coding gene on chromosome 3 (134,795,260 to 135,260,467, forward strand). Ensembl gene ENSG00000154928.
Subcellular location: Cell membrane; Early endosome membrane; Cell projection, dendrite
Subcellular location (Human Protein Atlas): Endoplasmic reticulum; Plasma membrane; Cytosol
Pathways (Reactome):
Developmental Biology: EPH-Ephrin signaling; EPH-ephrin mediated repulsion of cells; EPHB-mediated forward signaling; Ephrin signaling
Gene Ontology:
Molecular function: protein binding; transmembrane-ephrin receptor activity; ATP binding; axon guidance receptor activity; ephrin receptor activity; protein kinase activity; protein tyrosine kinase activity; protein-containing complex binding; transmembrane receptor protein tyrosine kinase activity
Biological process: angiogenesis; cell chemotaxis; cell-substrate adhesion; ephrin receptor signaling pathway; protein autophosphorylation; regulation of ERK1 and ERK2 cascade; regulation of JNK cascade; axon guidance; central nervous system projection neuron axonogenesis; dendritic spine development; dendritic spine morphogenesis; detection of temperature stimulus involved in sensory perception of pain; establishment of cell polarity; negative regulation of satellite cell differentiation; negative regulation of skeletal muscle satellite cell proliferation; neural precursor cell proliferation; neurogenesis; positive regulation of synapse assembly; retinal ganglion cell axon guidance; skeletal muscle satellite cell activation; cell migration; cell surface receptor protein tyrosine kinase signaling pathway; hindbrain tangential cell migration; modulation of chemical synaptic transmission; system development
Cellular component: early endosome membrane; extracellular exosome; plasma membrane; cytosol; dendrite; extracellular region; axon; cytoplasm; filopodium tip; glutamatergic synapse; membrane; membrane raft
Genetic constraint (gnomAD): Loss-of-function variants: 30 observed, 92.2 expected, observed/expected ratio (o/e) 0.33, 90% interval 0.24 to 0.44. The upper end of that interval is the gene's LOEUF score, 0.44, which puts it in group 1 of 6, group 1 being the genes least tolerant of losing a copy. Missense variants: 1,052 observed, 1,359.5 expected, observed/expected ratio (o/e) 0.77, 90% interval 0.74 to 0.81. Synonymous variants: 521 observed, 509.71 expected, observed/expected ratio (o/e) 1.02, 90% interval 0.95 to 1.1.
Homologues: Orthologues: chimpanzee EPHB1 (99% identical), macaque EPHB1 (99% identical), pig EPHB1 (99% identical), mouse Ephb1 (99% identical), rat Ephb1 (99% identical), rabbit EPHB1 (99% identical), tropical clawed frog ephb1 (91% identical), guinea pig EPHB1 (65% identical), zebrafish ephb1 (60% identical), dog EPHB1 (55% identical). Paralogues in human: EPHB2 (73% identical), EPHB3 (71% identical), EPHA4 (59% identical), EPHA5 (57% identical), EPHA7 (57% identical), EPHB4 (55% identical), EPHA3 (55% identical), EPHA6 (55% identical), EPHA8 (52% identical), EPHA2 (48% identical), EPHA10 (43% identical), EPHA1 (42% identical), and 41 more.
Diseases named in the same sentence as EPHB1 in open-access papers:
EPHB1 is named in the same sentence as 74 diseases in open-access papers, as found by Europe PMC text mining. Sharing a sentence is not in itself a finding about the gene and the disease. The quoted sentences say what the papers report.
glioma (10 papers, 2015 to 2025). A benign or malignant brain and spinal cord tumor that arises from glial cells (astrocytes, oligodendrocytes, ependymal cells). "Although EphB1 expression levels are similar across glioma grades, only EphB1 is associated with improved survival in malignant gliomas." (PMID 41200151, 2025). "Towards this direction, EPHB4/ephrin-B2 signaling is explored as an antiangiogenic target, with anti-EPHB4 monoclonal antibodies successfully blocking EPHB4 signaling, while inhibition of EPHA2 and EPHB1-3 forward signaling in gliomas is associated with a dose-dependent reduction in cell invasion." (PMID 38612645, 2024). "However, the underlying action mechanism of EphB1 in glioma remains elusive." (PMID 28194092, 2017). "Mechanistically, EphB1 lacks detectable tyrosine phosphorylation in glioma cells and, when overexpressed, inhibits ephrin-B2-induced migration and invasion both in vitro and in vivo." (PMID 41200151, 2025). "Specifically, the observation that a high expression of EPHA2 in neuroblastoma, EPHB1 in glioma, EPHB6, ephrin-B2, and ephrin-B3 in neuroblastoma correlates with a better prognosis is in line with a tumor-suppressive role of these EPHs." (PMID 38612645, 2024). "On the other hand, high expression levels of EPHA2 in neuroblastoma, of EPHB1 in glioma, and of EPHB6, ephrin-B2 and ephrin-B3 in neuroblastoma confer a better prognosis." (PMID 38612645, 2024). "Enhanced EphB1 signaling reduces the migration and invasion of glioma, suggesting a fairly widespread role in reducing cell motility." (PMID 37527777, 2023). "The results indicated that IBSP, MEOX2, and EPHB1 were inclined to express highly in glioma tissues compared with the adjacent relatively normal tissues, while the expression of NOG and GFRA1 tended to decrease in glioma tissues." (PMID 37501725, 2023). "By now, the direct evidences that clarify the mechanism of EphB1 in inhibiting glioma cell migration and invasion are limited." (PMID 28194092, 2017). "It is unclear which molecules are implicated in the phenotypic changes of glioma cells downstream of ephrin-B2 and how EphB1-ephrin-B2 interactions cooperatively regulate the cellular behavior of glioma cells." (PMID 28194092, 2017). "Quantitative real-time PCR and western blotting assays indicated that U87 and U251 glioma cells display low levels of mRNA and undetectable protein of EphB1." (PMID 28194092, 2017). "We are now designing experiments to determine the detailed action mechanism of EphB1 in inhibiting the migration of glioma cells." (PMID 28194092, 2017). "A reduction in EphB1 expression level was detected in a wide array of types of tumors such as glioma, gastric cancer, colorectal cancer, ovary serous carcinoma, and renal cell carcinoma." (PMID 28194092, 2017). "It is proposed that ligand-dependent EphB1 signaling appears to serve as a negative regulator of glioma cell motility, and its high expression is a positive predictor for survival of GBM patients." (PMID 28194092, 2017). "In contrast, enhanced EphB1 signaling has been shown to decrease migration and invasion in glioma cell lines." (PMID 25879388, 2015). "Since EphB1 plays a key function in the development and progression of other cancers, such as glioma, esophageal, colorectal and gastric cancers, we sought to better define the role of this receptor in medulloblastoma." (PMID 25879388, 2015). "Similar to its role in CRC, EphB1 plays a tumor suppressor role in glioma." (PMID 37527777, 2023). "In particular, in GBM, patients with higher levels of EPHB1 expression have a longer survival rate, which may be related to the enhanced positive EphB1 signaling reducing the migration and invasion of glioma." (PMID 37501725, 2023). "However, EphB1 partially abrogates the migration and invasion induced by ephrin-B2 reverse signaling in glioma cells." (PMID 28194092, 2017). "In addition to the tumor-suppressing role in glioma, EphB1 also promotes tumorigenesis in medulloblastoma." (PMID 28194092, 2017).
glioma (continued). "The functions of EphB1/ephrins signaling in glioma are now beginning to be uncovered." (PMID 28194092, 2017). "Other fc3 genes in the curated set, FERMT1, TMEM100, DYNLT3, EPHB1, IGFBP2, NNMT, and SH3GL2 all show direct evidence to a relationship with glioma biology and patient prognosis." (PMID 39941811, 2025). "An in vivo analysis showed that the mRNA level of EphB1 expression did not vary across different glial tumor grades except for the increased expression level of EphB1 in oligodendroglioma compared with normal brain specimens." (PMID 28194092, 2017).
medulloblastoma (8 papers, 2015 to 2025). A malignant, invasive embryonal neoplasm arising from the cerebellum. "In medulloblastoma, elevated expression of EphB1 and EphA4 is associated with enhanced angiogenesis and migratory capacity, contributing to tumor progression." (PMID 41200151, 2025). "This is an important finding providing further evidence that EphB1 loss plays a crucial role in enhancing the sensitivity to radiation therapy in medulloblastoma." (PMID 25879388, 2015). "Importantly, our data indicate that EphB1 loss enhances radiation sensitivity in vivo as observed in the genetically modified mouse model of medulloblastoma." (PMID 25879388, 2015). "EphB1 is also upregulated in subtype D medulloblastomas, which are characterized by axon guidance and neuronal differentiation signatures, suggesting its involvement in tumor plasticity." (PMID 41200151, 2025). "EPHB1 and EPHB3 are overexpressed in rhabdomyosarcoma tumor cells, while EPHB2 high-level expression has been reported in medulloblastoma tumor tissue samples, in NF2-deficient meningioma cell lines, and rhabdomyosarcoma tumor cells." (PMID 38612645, 2024). "We should note, though, that for certain EPH/ephrin members, such as EPHB1 in medulloblastoma and EPHB2 in ependymoma, the reported variable levels of expression render the characterization of their role in tumorigenesis ambiguous." (PMID 38612645, 2024). "While ephrin-B1 is uniquely dysregulated in medulloblastoma, differential effects of ephrin-B1 and ephrin-B2 knockdown on phosphorylation of EphB1/B2 and Src suggest alterations in reverse signaling in medulloblastoma cells." (PMID 29682554, 2018). "The reduction in growth and increase in radiosensitivity of medulloblastoma cells by EphB1 knockdown further substantiate the involvement of this receptor in maintaining the tumor cell phenotype." (PMID 29682554, 2018). "The high expression level of EphB1 in part of brain tumors, like medulloblastoma, has raised interest in exploring new strategies to target EphB1 receptors for cancer therapy." (PMID 28194092, 2017). "A recent study found that mRNA and protein expression levels of EphB1 are high in human medulloblastoma cell lines Daoy and UW228." (PMID 28194092, 2017). "Using both human medulloblastoma cell lines and genetically engineered mouse models, we investigated the role of EphB1 in medulloblastoma cell growth, migration, and radiosensitization." (PMID 25879388, 2015). "Our data suggest that both these lines express considerable levels of EphB1 receptor and thus serve as appropriate model systems to study the effects of EphB1 knockdown on radiosensitization in medulloblastoma." (PMID 25879388, 2015). "Taken together, our findings establish that EphB1 plays a key role in medulloblastoma cell growth, viability, migration, and radiation sensitivity, making EphB1 a promising therapeutic target." (PMID 25879388, 2015). "EphB1 transcript levels were also found to be significantly upregulated in medulloblastoma tumor spheres with high self-renewing ability compared to tumor spheres with low self-renewing ability." (PMID 25879388, 2015). "As EphB1 has been reported to promote migration and chemotaxis in several systems, we next investigated the impact of EphB1 knockdown on medulloblastoma cells in an electrical impedance-based migration assay." (PMID 25879388, 2015). "In view of this, inhibition of cyclin E following EphB1 knockdown likely plays a role in the observed inhibition of medulloblastoma tumor growth." (PMID 25879388, 2015). "To assess the role of EphB1 in medulloblastoma, we next attempted to knockdown EphB1 expression using siRNA approach." (PMID 25879388, 2015). "Our results indicate that EphB1 knockdown significantly decreases the migratory ability of medulloblastoma cells in culture." (PMID 25879388, 2015). "Despite these important findings, no additional studies have been reported to date that directly investigate the role of EphB1 in medulloblastoma tumorigenesis." (PMID 25879388, 2015).
medulloblastoma (continued). "Since, EphB1 is widely expressed in medulloblastoma, we analyzed the expression of EphB1 in human medulloblastoma cell lines DAOY and UW228." (PMID 25879388, 2015). "We assessed the expression and functional role of EphB1 in medulloblastoma cell lines and engineered mouse models." (PMID 25879388, 2015). "We evaluated the expression of EphB1 in a human medulloblastoma cell line, DAOY, and found EphB1 to be expressed at both the mRNA and protein level." (PMID 25879388, 2015). "Gene expression analyses of the DAOY medulloblastoma cell line further established that EphB1 is highly upregulated in migrating medulloblastoma cells, compared to non-invasive tumor cells at the primary tumor site." (PMID 25879388, 2015). "For example, overexpression and activation of EphB2, a receptor closely related to EphB1, in medulloblastoma cell lines has been shown to reduce cell adhesion and enhance invasion in vitro." (PMID 25879388, 2015). "Herein, we show that knockdown of EphB1 decreased medulloblastoma cell growth and migration, and increased the radiosensitivity of the medulloblastoma cell line in vitro." (PMID 25879388, 2015). "Our results are in agreement with published reports suggesting a role of EphB1 in medulloblastoma tumorigenesis." (PMID 25879388, 2015). "To examine the possible effects of EphB1 on radiosensitivity in vivo, we generated a genetically engineered EphB1 knockout mouse medulloblastoma model (EphB1−/−Smo) by crossing the transgenic ND2-SmoA1 medulloblastoma line with our mice deleted of EphB1." (PMID 25879388, 2015). "The influence of EphB1 suppression on medulloblastoma tumorigenesis makes EphB1 a potential candidate for the development of targeted therapies." (PMID 25879388, 2015). "Despite its generally high levels of expression, some studies report reduced EphB1 levels in specific medulloblastoma lines (DAOY, Res-220, UW-426) compared to normal cerebellum, suggesting context-dependent regulation or inhibitory mechanisms within certain tumor environments." (PMID 41200151, 2025). "Interestingly, EPH inhibition can be exploited to enhance the effectiveness of the currently applied treatment modalities, considering that EPHB1 knockdown in medulloblastoma cells has been shown to enhance cellular radiosensitization." (PMID 38612645, 2024). "Consequently, when EphB1 was knocked down in the DAOY human medulloblastoma cell line, migration was inhibited." (PMID 33430066, 2021). "Conversely, EphB1 seems to act as a tumour promoter in medulloblastoma." (PMID 33430066, 2021). "Importantly, EphB1 knockdown can enhance the sensitivity of medulloblastoma to ionizing radiation sensitivity in vitro and in vivo." (PMID 28194092, 2017). "Furthermore, our data provide mechanistic insights into how EphB1 downregulation affects medulloblastoma cell growth and survival." (PMID 25879388, 2015). "This suggests the involvement of other pathways such as DNA damage repair that might be playing a role in EphB1 knockdown mediated radiosensitization in medulloblastoma cells." (PMID 25879388, 2015). "Our findings indicate that EphB1 downregulation reduces migration and enhances cellular sensitization to radiation therapy by increasing the percentage of cells in the G1 phase of the cell cycle ultimately decreasing medulloblastoma cell growth and viability." (PMID 25879388, 2015). "Furthermore, EphB1 knockdown enhanced cellular radiosensitization of medulloblastoma cells in culture and in a genetically engineered mouse medulloblastoma model." (PMID 25879388, 2015). "Collectively, our results are consistent with the hypothesis that upregulation of EphB1 contributes to the aggressive and invasive nature of medulloblastoma." (PMID 25879388, 2015). "However, ephrin-A5 is a promiscuous ligand that binds to multiple other Eph A and B receptors including EphB1 and EphB2, both of which are present in medulloblastoma tumors." (PMID 26345456, 2015).
medulloblastoma (continued). "Thus, our data clearly underscore the relevance of EphB1 knockdown in inhibiting medulloblastoma cell growth by affecting cell cycle, proliferation, and cell survival pathways." (PMID 25879388, 2015). "This could be a potential mechanism by which EphB1 contributes to medulloblastoma metastasis." (PMID 25879388, 2015). "EphB1 is frequently expressed in medulloblastoma, particularly in SHH and non-SHH subtypes, with over 90% of tumors showing diffuse immunopositivity." (PMID 41200151, 2025). "For instance, IQGAP3, EPHB1, ROR2 and RCC2 were demonstrated to obviously promote cell migration, invasion, and epithelial-to-mesenchymal transition in hepatocellular carcinoma, medulloblastoma and breast carcinoma, respectively." (PMID 34922560, 2021). "Furthermore, EphB1 can functionally interact with the epidermal growth factor receptor (EGFR), contributing to the metastatic behavior of medulloblastoma cells." (PMID 28194092, 2017). "Similar results were obtained with another well-studied medulloblastoma cell line, UW228, where EphB1 knockdown showed an approximately 11% increase in the percentage of cells in the G1 phase as compared to the control non-specific siRNA (Ns-siRNA) transfected group." (PMID 25879388, 2015). "Our results show an appreciable decrease in the levels of phosphorylated EGFR and total EGFR following EphB1-specific siRNA treatment in DAOY cells, suggesting that the EphB1 receptor might be contributing to the metastatic behavior of medulloblastoma cells by functionally interacting with EGFR." (PMID 25879388, 2015).